HLA-G (major histocompatibility complex, class I, G)
Diseases named in the same sentence as HLA-G in open-access papers (continued):
Sharing a sentence is not in itself a finding about the gene and the disease.
tumor (continued). "Conversely, transcription activation of non-classical HLA-G through demethylation, and resultant HLA-G protein expression, may facilitate tumour cells to evade immunosurveillance." (PMID 18397301, 2008). "Unfortunately, it was not possible to evaluate tissue HLA-G expression and inflammatory infiltrate in our cohort due to the impossibility of recovering formalin-fixed and paraffin-embedded samples in most cases, limiting our comprehension about its relationship with tumor microenvironment." (PMID 41268555, 2025). "Therefore, targeting HLA-G/LILRB pathways with antibodies, alone or in combination with other ICIs, might constitute a promising strategy for breaking down tolerance in tumors and promoting rejuvenation of exhausted tumor-infiltrating immune cells." (PMID 38785789, 2024). "In addition, tumor cells were negative for HLA-A and positive for HLA-G." (PMID 35681761, 2022). "Moreover, tumor cells were negative for Human Leukocyte Antigen G (HLA-G)." (PMID 35681761, 2022). "HLA-G, which was a nonclassical major histocompatibility complex molecule with immunomodulatory properties, could result in immune suppression, driving tumor growth and progression by HLA-G/ILT-2/-4 (HLA-G/ILT) signaling." (PMID 36380313, 2022). "Since HLA-G is not expressed by primary NB tumor cells, it can be postulated that the ability of BM-infiltrating NB cells to survive in the BM and restart proliferation after an apparent cure could be a consequence of the HLA-G immune suppressive activity." (PMID 34069335, 2021). "Further, tumour cells may express the non-canonical MHC molecule HLA-G." (PMID 28404796, 2017). "In addition, it is not clarified whether HLA-G-bearing EVs or free soluble HLA-G (sHLA-Gfree) are produced by tumor cells and whether both subcomponents contribute to immune evasion of tumor cells." (PMID 27199995, 2016). "Given their a broad specificity for HLA-G isoform detection, results obtained by using mAb 4H84 and HGY could only read the combination of certain types of HLA-G isoform expression; however, the fine types of isoforms expressed in tumour lesions remains undistinguished." (PMID 25689063, 2015). "Another limit is the lack of biological samples such as tumour or plasma samples to correlate genetic data with tissue and/or soluble levels of HLA-G to sustain functional hypothesis about the regulatory role of these SNPs, even if previous published studies support consistent data." (PMID 26633805, 2015). "In contrast, HLA-G expression on TILs was not linked to a decrease in survival rates, suggesting that it is HLA-G expression on tumour cells, rather than on TILs, that orchestrates biological behavior of MIBC and thus HLA-G’s impact on clinical outcomes." (PMID 39469714, 2024). "HLA-G, a nonclassical MHC component, plays a crucial role in immune tolerance and is expressed in various immune and tumor cells." (PMID 38342925, 2024). "Moreover, since there are several spliced forms of HLA-G, post-translational regulation within the TME may play a dominant role in protein expression which could ultimately change the impact of HLA-G expression (membrane-bound or soluble) and function in the tumor niche." (PMID 38067396, 2023). "HLA-G is the non-classic MHC-I gene and the ligand for the inhibitory receptor of KIRs, which are highly expressed in numerous tumor cells." (PMID 36560427, 2022). "HLA-G is a member of the non-classical MHC family and plays a key role in tumor cell escape from host immune surveillance by inhibiting immune cell activities." (PMID 36207500, 2022). "HLA-G, as a non-classical major histocompatibility complex (MHC) class I molecule, often directly inhibited natural killer (NK) and tumor-specific T cells, and expressed in up to 34% EWS samples." (PMID 35719404, 2022).
tumor (continued). "Another non-classical HLA molecule is HLA-E, which, like HLA-G, has immunosuppressive properties, and studies have found higher levels of HLA-E transcripts detected in all RCC cell lines and tumor lesions compared to standard renal epithelium." (PMID 33767709, 2021). "Antibodies against HLA-G/KIR2DL4 combined with trastuzumab and NK cells, but not blocking antibodies alone, suppressed tumor growth in vivo, suggesting that these blocking antibodies exert a tumoricidal role at least partially by enhancing ADCC activity." (PMID 34158475, 2021). "However, the expression of HLA-G has been found in various types of tumors, and the level of its expression frequently correlates with high-grade histology and poor prognosis, raising the possibility that it may play a negative role in tumor immunity." (PMID 33425752, 2020). "Although authors reported that CAR-redirected NK cells were unable to prevent or reduce tumor growth in pre-clinical models, they identified non-classical MHC class I molecule, HLA-G, as key factor in the tumor immune escape from NK cells." (PMID 32707982, 2020). "HLA-G transcription was found to be induced upon heat shock in tumor cell lines, by heat shock transcription factor 1 (HSF1) binding to a heat shock element (HSE) present in HLA-G but not in other HLA class I genes." (PMID 25870595, 2015). "Investigations of cytotoxicity of dNK and donor-derived tumor cells are rare and no sufficient information is available about the role of LIR-1 in the absence of HLA-G." (PMID 22844324, 2012). "HLA-G, a non-classical class I major histocompatibility complex (MHC) molecule, represents a key immune checkpoint that contributes to an immunosuppressive tumour microenvironment, facilitating immune evasion by tumour cells." (PMID 40155873, 2025). "Yet, in experimental in vitro model, ectopic expression of HLA-G by myeloid THP-1 cells but not by EwS tumor cells impeded functionality of CAR T cells, suggesting that immunosuppressive effects of HLA-G could be mediated by myeloid cells in the TME." (PMID 36612267, 2022). "In support of this hypothesis, HLA-G did have a functional impact on antigen-specific CART responses when artificially expressed on a monocytic cell, rather than on the tumor cell itself." (PMID 34201079, 2021). "Previous studies have found that M2 macrophages with immunosuppressive properties can promote tumor immune escape by upregulation of non-classical MHC class I molecules (e.g., HLA-E and HLA-G), inhibitory ligands for T cells, apoptosis receptors (e.g., PD-L1, TRAIL, and B7-H4), and SIRP-alpha." (PMID 34717747, 2021). "The retrospective study clearly demonstrates high expression of VEGF-A, HLA-G and ILT4, but does not inform us whether these molecules are co-expressed in the same areas of the tumor." (PMID 32620162, 2020). "Resulting β2M-free HLA-G isoforms could still be immunosuppressive and inhibit the immune response, particularly the NK immune response that should lyse MHC class I negative tumor cells." (PMID 32922387, 2020). "In some patients, a high degree of HLA-G expression was observed in all selected areas; however, in other patients, HLA-G expression was only found in some but not all areas among CA9+ ccRCC tumor cells." (PMID 30319626, 2018). "Also, HLA-G interaction with LILRB1 on NK cells and the resultant inhibitory function do not require tumor cell lipid raft integrity." (PMID 24818168, 2014). "They analyzed GSC derived from primary tumor samples by mass cytometry, and the GSC expressed normal levels of NK cell activation receptor ligands (ULBP2, ULBP3, VIM) and upregulated levels of NK cell inhibitory receptor ligands (HLA-A, HLA-B, HLA-C, HLA-E, HLA-G, PCNA) compared with non-GSC." (PMID 34638384, 2021). "HLA-G may also be pathologically expressed by (i) non-rejected allografts, (ii) lesion-infiltrating antigen presenting cells (APC) during inflammatory diseases, and (iii) tumor tissues and their tumor infiltrating APC." (PMID 21779321, 2011).
tumor (continued). "Furthermore, since the increased expression of HLA-G and TIGIT correlated with a better clinical outcome of patients, these data suggested that, at least in this cohort of patients, these two molecules are not involved in the inhibition of anti-tumor T cell response." (PMID 35328349, 2022).
cancer (261 papers, 2006 to 2026). A tumor composed of atypical neoplastic, often pleomorphic cells that invade other tissues. "Genetic variability within the HLA-G gene, particularly polymorphisms located in regulatory regions such as the 14-base pair insertion/deletion, has been associated with cancer susceptibility, disease progression, and adverse prognosis." (PMID 42083155, 2026). "In the context of cancers, several studies have shown that HLA-G expression in malignant lesions is associated with cancer progression and short patient survival, making it a promising target for cancer immunotherapy." (PMID 41181133, 2025). "Since then, over the past three decades, the immunosuppressive functions and underlying mechanisms of HLA-G have been intensively explored, and its clinical significance has been evaluated in more than 30 types of cancer." (PMID 41194925, 2025). "Pathologically, HLA-G is expressed in many different types of cancer and is implicated in oncologic immune tolerance." (PMID 38473890, 2024). "Numerous studies have explored the relationship between the HLA-G 14 bp ins/del variant and various cancer risks, but the findings have been inconsistent." (PMID 39594832, 2024). "Elevated HLA-G levels have been linked to numerous physiological and pathological conditions, such as cancer, while lower levels are associated with autoimmune and inflammatory diseases, in line with the results described herein." (PMID 39549048, 2024). "Multiple studies support the association between the progression of cancer and an altered expression of HLA class Ib molecules, particularly HLA-G, with a concomitant downregulation of classical HLAs." (PMID 39766165, 2024). "Many studies assessed the association of the HLA-G 14 bp ins/del variant with different types of cancer risks, but with contradictory results." (PMID 38391781, 2024). "The co-expression of ILT4 and HLA-G is linked to increased lymph node invasion, advanced cancer stages, and reduced overall survival." (PMID 39766165, 2024). "The abnormal expression of HLA-G in different cancers is associated with poor clinical outcomes in patients, so increasing attention has been given to HLA-G as an immune checkpoint in cancer." (PMID 36960057, 2023). "Since membrane HLA-G expression is linked with STAT3 activation in cancer cells, we chose the membrane localizing SPAG9 protein from the candidate HLA-G protein partners for further investigation." (PMID 36780531, 2023). "Rs1063320, rs1610696, rs1704, rs1707, rs1710, rs17179101, and rs17179108 in HLA-G are associated with increased cancer susceptibility in the Brazilian population." (PMID 38025894, 2023). "In colorectal cancer, SPP1-expressing TAMs were located in the invasive front, and the SPP1 signal was suggested to be involved with cancer cell expression of HLA-G, which in turn was associated with cancer cell escape from the immune system." (PMID 37190178, 2023). "In conclusion, our study provides evidence that certain HLA-G 3’UTR polymorphisms can influence sHLA-G levels in cancer patients’ peripheral blood, especially 14 bp Ins/Del (rs371194629) and 3142 C/G (rs1063320)." (PMID 36618382, 2022). "Human leukocyte antigen‐G (HLA‐G) is implicated in several cancers and is considered to be an immune checkpoint regulator." (PMID 35759240, 2022). "Among the cancer-produced immunosuppressive cytokines, IL-10 is responsible for the overexpression of HLA-G, which is implicated in the immune escape." (PMID 36437782, 2022). "Both genetic (polymorphisms) and protein expression studies confirm that HLA-G overexpression in cancer is related to faster disease progression and worse clinical outcome." (PMID 35154112, 2022). "Different HLA-G alleles were shown to have a distinctive role in the reproductive system of females and males and also in other cancers and infections by facilitating their escape from immune surveillance." (PMID 35363864, 2022).
cancer (continued). "HLA-G and sHLA-G regulation is associated with poor treatment results in cancer patients, implying a role in cancer cells’ immune escape mechanism." (PMID 36551617, 2022). "It is now widely accepted that HLA-G is a critical marker of immunotolerance in cancer immune evasion and is strongly associated with disease progress and prognosis in cancer patients." (PMID 35154112, 2022). "A number of studies have indicated that HLA-G polymorphisms are associated with HLA-G expression, cancer susceptibility and cancer development." (PMID 34206399, 2021). "Except for one study, the verdict on the association between HLA-G expression and clinical outcome of GC patients is relatively unanimous in comparison to other carcinoma types." (PMID 34361031, 2021). "It is implied that in the carcinoma types where HLA-G expression was associated with poor clinical patient outcome, HLA-G expression plays a functional role in disease progression and, therefore, is a candidate immune checkpoint molecule." (PMID 34361031, 2021). "Third, potential mechanisms underlying the heterogeneity of HLA-G in cancers remain to be uncovered." (PMID 33329527, 2020). "Progression of cancer is often associated with altered expression of HLA molecules and multiple studies support that upregulation of HLA class Ib expression, especially HLA-G, is a mechanism, whereby tumors are able to escape immunological surveillance." (PMID 32560316, 2020). "HLA-G expression can also be induced during inflammatory-associated diseases such as cancer, transplantation, autoimmune disease, and infection." (PMID 33425752, 2020). "For example, IL-10 not only down-regulates HLA-I but also up-regulates HLA-G, and causes immune escape in cancer cells." (PMID 32547401, 2020). "In cancer cells, the increased HLA-G expression is closely correlated with the loss of some HLA-G-targeting miRNAs." (PMID 32222150, 2020). "The present analysis includes all eligible studies to precisely explore the association of the HLA-G 14-bp Ins/Del polymorphism with cancer susceptibility." (PMID 30962267, 2019). "Larger sample sizes and well-designed case–control experiments with various types of cancer in diverse ethnicities are needed to further verify the relationship between the HLA–G 14-bp Ins/Del variant and cancer risk." (PMID 30962267, 2019). "Because HLA-G is considered to be pro-tumorigenic immunosuppressive molecule, the C allele which is potent to produce more HLA-G protein plausibly should be associated with cancer susceptibility." (PMID 31759373, 2019). "There were a larger number of studies that had evaluated the correlation between the HLA-G 14-bp Ins/Del polymorphism and the susceptibility to different types of cancer." (PMID 30962267, 2019). "Several published studies have indicated that some polymorphisms of the HLA-G gene are related to cancer development." (PMID 30962267, 2019). "Apart from pregnancy, HLA-G has been described associated with chronic viral infections, cancer and in vitro fertilization success." (PMID 31235762, 2019). "Since these reports, many new case–control studies have explored the correlation between the HLA-G 14-bp Ins/Del polymorphism and the risk of different types of cancer; however, the results of these subsequent studies were still inconclusive." (PMID 30962267, 2019). "There were not enough appropriate studies in some subgroups, weakening the statistical power to investigate the real relationship between the HLA-G 14-bp Ins/Del polymorphism and cancer risk." (PMID 30962267, 2019). "There is however a limited information on how HLA-G is implicated in various cancers in African population." (PMID 31759373, 2019). "In contrast, some reports have also described opposite associations of HLA-G expression with prognosis in some cancer indications." (PMID 31013867, 2019).
cancer (continued). "Some other studies have associated HLA-G with cancer progression, revealed by higher expression level of HLA-G in high stage and metastasized cancers than in low stages and non-metastasized cancers." (PMID 31759373, 2019). "In this meta-analysis, we evaluated the HLA-G 14-bp Ins/Del polymorphism and cancer risk relationship with all qualified case–control studies." (PMID 30962267, 2019). "Our results demonstrated, for the first time, a significant relationship between the HLA-G 14-bp Ins/Del polymorphism and a decreased overall cancer risk." (PMID 30962267, 2019). "Begg’s and Egger’s tests were conducted to explore the potential for publication bias in assessment of the relationship between the HLA-G 14 Ins/Del polymorphism and cancer risk in all genetic models." (PMID 30962267, 2019). "In order to measure HLA-G molecules in the serum of autoimmune and cancer patients, enzyme linked immunosolvent assays (ELISAs) were developed using monoclonal antibodies against HLA-G." (PMID 31779209, 2019). "To date, a number of studies have explored the relationship between the HLA-G gene polymorphisms and the risk of cancer." (PMID 30962267, 2019). "It is now widely accepted that HLA-G is a critical marker of immunotolerance in cancer cell immune evasion and is strongly associated with disease progress and prognosis for cancer patients." (PMID 30319626, 2018). "HLA-G expression by solid tumors has been associated with worse prognosis and higher grade in numerous cancers including kidney, ovary, breast, lung, colon." (PMID 30237859, 2018). "Some 3′UTR SNPs of the HLA-G gene were shown to be independently associated with cancer susceptibility, and recently, with CRC prognosis." (PMID 28653974, 2017). "Lately, the predictive value regarding the genetic predisposition to express different levels of HLA-G was explored in different human cancer cell lines with in vitro functional approaches, confirming the intermediate producer signature for UTR-2 haplotype." (PMID 28653974, 2017). "HLA-G gene function has been implicated in a number of diseases such as cancer and in pregnancy outcome." (PMID 27525330, 2016). "The identification of molecular mechanisms implicated in the HLA-G induction in these conditions is of crucial importance in the scope of developing future anti-cancer therapies and more particularly immunotherapies." (PMID 27577073, 2016). "Association of HLA-G expression in cancer lesions with clinicopathological parameters, and HLA-G 14-bp sequence status." (PMID 24870375, 2014). "HLA-G expression is induced following IL-10 stimulation in experiments in vitro and is associated with IL-10 expression in vivo in a context of cancer." (PMID 24839609, 2014). "EVs, especially those associated with HLA-G, may be related to cancer progression or phenotype modification of benign skin lesions, such as nevi." (PMID 41268555, 2025). "Additionally, HLA-G as an immunomodulatory molecule has been associated with many diseases, including cancer." (PMID 38391781, 2024). "HLA-G is engaged in the evolution of normal tissue cells and their transformation into malignant cells, and its expression and polymorphisms have been linked to precancerous lesions and cancer susceptibility." (PMID 38310272, 2024). "More research is needed to determine the association between HLA-G and cancers." (PMID 38577332, 2024). "Moreover, although HLA‐G or PD‐L1 silencing increased the susceptibility of cancer cells to cytolysis by parental γδT cells, both Nb‐CAR‐γδT and Nb‐CAR.BiTE‐γδT cells still had superior cell‐killing activity compared to the parental γδT cells." (PMID 37078788, 2023). "HLA-G expression was associated with worse OS (HR 2.09, 95% CI = 1.67 to 2.63; P < .001), that was higher in gastric (HR = 3.40; 95% CI = 1.64 to 7.03), pancreatic (HR = 1.72; 95% CI = 0.79 to 3.74) and colorectal (HR = 1.55; 95% CI = 1.16 to 2.07) cancer." (PMID 37275862, 2023).